EZH2 (enhancer of zeste 2 polycomb repressive complex 2 subunit)
Diseases named in the same sentence as EZH2 in open-access papers (continued):
Sharing a sentence is not in itself a finding about the gene and the disease.
bladder cancer (continued). "Recent studies indicate that MALAT1 enhances the activity of the PRC2 complex in bladder cancer by interacting with the subunit SUZ12 but not the subunit EZH2 in PRC2." (PMID 26516927, 2015). "One study demonstrates previously that MALAT1 associates with PRC2 by interacting with SUZ12 but not EZH2 and that inhibition of MALAT1 decreases the binding of SUZ12 to the E-cadherin gene promoter in bladder cancer." (PMID 26516927, 2015). "NSC745885 down-regulated EZH2 in MBT2 and T24 bladder cancer cells with high baseline EZH2 expression levels, but not in SV-HUC-1 immortalized normal urothelial cells." (PMID 25431950, 2014). "Moreover, proliferation rates and metastasis of bladder cancer cells could be substantially regulated by the lncRNA SPRY4-IT1 (SPRY4 intronic transcript 1), mediated by its impact on the expression of enhancer of zeste homolog 2 (EZH2)." (PMID 34332611, 2021). "Moreover, we did not observe a correlation of ARID1A expression with EZH2 or H3K27me3 amounts in human bladder carcinomas." (PMID 30138427, 2018). "With respect to bladder cancer, miRNA profiling of bladder transitional cell carcinoma (TCC) samples has revealed that miR-101 is downregulated in TCC, and that miR-101 inhibits cell proliferation and colony formation in TCC cell lines through directly repressing the histone methyltransferase EZH2." (PMID 25658842, 2015). "Moreover, NSC745885 and doxorubicin both decreased EZH2 protein levels in drug-sensitive MGH-U1 bladder cancer cells, but only NSC745885, not doxorubicin, down-regulated EZH2 expression in multi-drug-resistant MGH-U1R bladder cancer cells." (PMID 25431950, 2014). "However, the baseline EZH2 expression levels in bladder cancer tissues did not correlate with the therapeutic response to neo-adjuvant chemotherapy among the 12 patients." (PMID 25431950, 2014). "Moreover, amounts of EZH2 protein and H3K27me3 were not significantly different, comparing urothelial bladder carcinomas strongly expressing ARID1A protein (median Remmele score: 12) to bladder cancer cases exhibiting ARID1A protein loss or only residual ARID1A expression (median Remmele score: 0)." (PMID 30138427, 2018).
pancreatic cancer (146 papers, 2009 to 2026). "Epigenetic repression of pro-inflammatory SASP genes—such as those encoding CCL2 and CXCL9/10—by enhancer of zeste homolog 2 (EZH2) has been shown to dampen immune cell infiltration in pancreatic cancer models." (PMID 40867884, 2025). "EZH2 is overexpressed in patients with pancreatic cancer and is associated with poorer clinical outcomes." (PMID 36902253, 2023). "For instance, aberrant expression of enhancer of zeste homolog 2 (EZH2) in pancreatic cancer cells has been linked to gemcitabine resistance, possibly due to the downregulation of the tumor suppressor p27Kip1." (PMID 34564701, 2021). "A high EZH2 expression has been reported being associated with poor disease outcome in different types of tumors, like breast, prostate, and pancreatic cancers." (PMID 30038060, 2019). "Previous reports found that EZH2 causes transcriptional silencing of the tumor suppressor gene E-cadherin, and that lower expression of E-cadherin in pancreatic cancer is correlated with increased migration and invasion." (PMID 26848980, 2016). "To further confirm the association of EZH2 and E-cadherin in pancreatic cancer, we assessed E-cadherin expression in the TMAs data." (PMID 26848980, 2016). "High EZH2 expression was associated with an especially poor prognosis for pancreatic cancer patients (P<0.05)." (PMID 26848980, 2016). "If EZH2 blocks p27 expression, silencing of EZH2 should be linked to a re-increase of p27 expression, as has been observed in pancreatic cancer cells." (PMID 21765901, 2011). "In addition, HOTAIR is caused resistance to TRAIL-induced apoptosis by modulating EZH2-mediated histone H3 lysine 27 trimethylation (H3K27me3) in pancreatic cancer cells." (PMID 38559560, 2024). "Meanwhile, AhR activation could enhance the EZH2 activity and increase its epigenetic silencing activity, which is a risk factor for environmental toxicant-associated pancreatitis and pancreatic cancer." (PMID 36635272, 2023). "In pancreatic cancer cells, the activation of AhR/EZH2 signaling axis causes epigenetic alteration." (PMID 36635272, 2023). "One study showed that loss of EZH2 promotes KRasG12D-driven oncogenesis in pancreatic cancer." (PMID 35269532, 2022). "This EZH2 dependency might generate a vulnerability in 30%–40% of pancreatic cancer patients whose tumors harbor mutations in the SWI/SNF complex." (PMID 31277415, 2019). "K-RAS oncogenic activation has been implicated in EZH2 up-regulation in pancreatic cancer." (PMID 28881737, 2017). "In this study, we investigated whether the serotonin (5-hydroxytryptamine, 5-HT) system plays an important role in gemcitabine resistance and the maintenance of pancreatic cancer stem cells (CSCs) in association with an Enhancer of zeste homolog 2 (EZH2), an epigenetic regulator of transcription." (PMID 34771469, 2021). "However, it remains unclear whether the expression of EZH2 is regulated by miR-124 in pancreatic cancer, and what the underlying mechanisms are." (PMID 33040049, 2020). "In parallel, we used the EZH2 inhibitor UNC1999 as a control to evaluate its impact on NeuroD1 expression in pancreatic cancer cells." (PMID 41225636, 2025). "Subsequent studies demonstrated that EZH2 is overexpressed in several solid malignancies, including lung, hepatocellular, colorectal, breast, and pancreatic cancers." (PMID 40004468, 2025). "On the other hand, studies have shown that PVT1 is involved in the induction of gemcitabine resistance by binding to the EZH2 and forming the PVT1/EZH2 complex in pancreatic cancer." (PMID 38559560, 2024). "Studies have demonstrated that elevated levels of EZH2 in gallbladder cancer cells promote tumor cell invasion, while inhibition of EZH2 has been shown to suppress migration and invasion in pancreatic cancer." (PMID 39043634, 2024). "UCA1 suppressed SOCS3 via EZH2 recruitment in PC cells, thus promoting malignant traits and Gem resistance in pancreatic tumor cells." (PMID 37580768, 2023).
pancreatic cancer (continued). "EZH2 can stimulate the migration and invasion of pancreatic cancer by inhibiting the expression of E-cadherin." (PMID 36902253, 2023). "CDK5 activates tumor-suppressive pathways in pancreatic cancer via EZH2 degradation and in NSCLC by DLC1 activation." (PMID 37993880, 2023). "In pancreatic cancer, increased expression of SOX4 and EZH2 is associated with poor patient prognosis." (PMID 36902253, 2023). "Anillin (ANLN) promoted the progression of pancreatic cancer through inducing EZH2 up-regulation by mediating the miR-218-5p/LASP1 signaling." (PMID 37604837, 2023). "Curcumin improved GEM sensitivity in pancreatic tumor cells via EZH2 blocking and its downstream target PVT1." (PMID 37580768, 2023). "In pancreatic cancer, EZH2 expression is significantly elevated, and inhibition of EZH2 expression inhibits proliferation and movement of pancreatic carcinoma." (PMID 38048186, 2023). "ANLN contributes to pancreatic cancer progression by regulating the EZH2/miR-218-5p/LASP1 signaling axis." (PMID 38144520, 2023). "EZH2, a PcG member and a subunit of polycomb repressor complex 2 that provokes gene silencing by histone trimethylation, participates in pancreatic cancer chemoresistance via turning off the p27 tumor suppressor gene." (PMID 35505363, 2022). "EZH2 promotes the progression of several cancer and promotes cell migration and invasion of pancreatic cancer cell lines." (PMID 36048239, 2022). "EZH2 is found in a variety of cancers, including breast, prostate, bladder, colon, lung, and pancreatic cancers, as well as anaplastic thyroid, nasopharyngeal, endometrial carcinomas, and lymphomas." (PMID 36316365, 2022). "EZH2 is also closely associated with the EMT of other tumors, such as pancreatic cancer, head and neck squamous cell carcinoma and esophageal cancer." (PMID 36230759, 2022). "Hypoxia contributes to CSCs enrichment via hyperactivation of VEGF, IL-6, and stemness-related genes like NANOG, OCT4, and EZH2, as shown in pancreatic tumor cells." (PMID 35505363, 2022). "It is reported that ANLN participates in the HMGA2-induced increase in the tumorigenicity of pancreatic cancer cells and through controlling the EZH2/miR-218-5p/LASP1 axis, ANLN deficiency dramatically reduces pancreatic tumor cell migration and invasion." (PMID 36199577, 2022). "In pancreatic cancer, Twist-1 promotes metastasis by interacting with EZH2 and downregulating the expression of proteins such as E-cadherin and p16." (PMID 35632705, 2022). "A recent report has documented that EZH2 can be suppressed by FBW7 in pancreatic cancer cells, thus restraining tumor cell migration and invasion." (PMID 34802056, 2021). "We observed a positive correlation between the protein levels of HAT1 and EZH2 in pancreatic cancer tissues (Spearman correlation coefficient r = 0.5899, P = 0.0005)." (PMID 34564701, 2021). "EZH2-mediated miR-139-5p regulated pancreatic cancer's epithelial-mesenchymal transition and lymph node metastasis." (PMID 34307682, 2021). "Accordingly, concomitant expression of NFATc1 and EZH2 was also detected in invasive pancreatic tumors of the fast-progressing KPC model and in a PDAC Patient-Derived Xenograft (PDX) model." (PMID 34943970, 2021). "To investigate the relationship between intrinsic gemcitabine resistance and the expression of EZH2 and 5-HT system genes in pancreatic cancer cells, we first compared the levels of resistance and those gene expressions between PDAC cell lines." (PMID 34771469, 2021). "Several researches showed that EZH2 was a drug-related resistant gene, our research also confirmed EZH2 made pancreatic cancer cells become insensitive to gemcitabine." (PMID 34564701, 2021). "LINC01133 promoted the loading of EZH2 to transcriptionally downregulate DKK1 in pancreatic cancer cells." (PMID 34178644, 2021). "EZH2 overexpression occurred in pancreatic cancer and it was positively correlated with lncRNA UCA1 expression." (PMID 34868904, 2021).
pancreatic cancer (continued). "MALAT1 and EZH2 epigenetically inactivated E-cadherin and potently enhanced invasion and migration of pancreatic cancer cells." (PMID 34178644, 2021). "Although EZH2 protein levels were reduced after HAT1 silencing, treatment with the proteasome inhibitor MG132 restored EZH2 protein levels in HAT1-knockdown pancreatic cancer cells." (PMID 34564701, 2021). "Tissue microarray of pancreatic cancer (n = 31) was used to conduct IHC analysis and ascertain the relationship between HAT1 and EZH2 in pancreatic cancer." (PMID 34564701, 2021). "More importantly, we found that HAT1 enhanced the expression of EZH2 in pancreatic cancer cells in this study." (PMID 34564701, 2021). "The long noncoding RNA PVT1 (lncRNA PVT1) has been shown to interact with enhancer of zeste 2 polycomb repressive complex 2 subunit (EZH2), promoting gemcitabine resistance in pancreatic cancer." (PMID 34564701, 2021). "We found that in pancreatic cancer cells, Twist1 interacts with Ring1B and EZH2 to regulate the expression of E-cadherin and p16 protein, thereby promoting the metastasis of pancreatic cancer." (PMID 33569740, 2021). "Further, we observed that SOCS3 underexpression occurred in pancreatic cancer and it was negatively correlated with EZH2." (PMID 34868904, 2021). "DNA methylation and EZH2-mediated H3K27 trimethylation were established for the first time to be responsible for the downregulation of LINC00261 in pancreatic cancer." (PMID 33122827, 2021). "Many studies showed that EZH2 was upregulated in various solid malignancies including lung, hepatocellular, colorectal, breast, and pancreatic cancer, etc.." (PMID 34381492, 2021). "Like this, many pieces of research have reported that lncRNA binds to EZH2 protein that suppresses apoptosis in osteosarcoma, colon cancer, pancreatic cancer, renal cancer, and lung cancer." (PMID 33050646, 2020). "Western blot was used to detect the expression levels of pro-apoptotic caspase-3, BAX and anti-apoptotic Bcl-2, and the results confirmed that the miR-124 mimic tempted the apoptosis in pancreatic tumor cells, which was reversed by overexpression of EZH2." (PMID 33040049, 2020). "F-box and WD repeat domain-containing 7 (FBW7), a novel E3 ligase of EZH2, can mediate the phosphorylation, ubiquitination, and degradation of EZH2 with the involvement of the activated CDK5 kinase in pancreatic cancer." (PMID 32723346, 2020). "In pancreatic cancer, Twist recruited Ring1B and enhancer of zeste homolog 2 (EZH2), members of polycomb family, to bind to the promoter of E-cadherin and suppressed its transcription, inducing EMT." (PMID 32587480, 2020). "Afterwards, the roles of miR-124 on the expression and function of EZH2 in pancreatic tumors were determined by dual luciferase reporter assay." (PMID 33040049, 2020). "The results revealed that the miR-124 expression significantly decreased in pancreatic tumors, while the EZH2 expression in pancreatic cancer tissues was remarkably elevated." (PMID 33040049, 2020). "The profiles of EZH2 related CpGs in pancreatic cancer stem cells are distinguished from pancreatic tumor and normal samples as those loci are largely methylated in pancreatic cancer stem cells." (PMID 31324166, 2019). "In pancreatic cancer, EZH2 downregulation induced the expression of miR-139-5p via H3K27me3, thereby repressing the progression of pancreatic cancer." (PMID 31395079, 2019). "In functional assays, EZH2 restoration in pancreatic cancer cells transfected with ANLN RNAi rescued the inhibition of cell proliferation, colony formation, cell migration and cell invasion caused by ANLN knockdown." (PMID 31395079, 2019). "EZH2 upregulation induced by ANLN promoted pancreatic cancer cell progression by miR-218-5p/LASP1 signaling axis." (PMID 31395079, 2019). "EZH2 upregulation or miR-218-5p downregulation partially reversed the tumor-suppressive effect of ANLN downregulation on pancreatic cancer cell progression." (PMID 31395079, 2019).
pancreatic cancer (continued). "In pancreatic cancer, EZH2 is upregulated and induces pancreatic cancer cell proliferation, cell migration and cell invasion in vitro and tumor growth and metastasis in vivo by inhibiting the expression of miR-218-5p." (PMID 31395079, 2019). "ANLN contributed to pancreatic cancer progression by regulating EZH2/miR-218-5p/LASP1 signaling axis." (PMID 31395079, 2019). "Subsequent studies showed that EZH2 is upregulated in various solid malignancies including lung, hepatocellular, colorectal, breast and pancreatic cancer etc., and is shown to have prognostic significance in a variety of solid cancers." (PMID 29556394, 2018). "FBXW7 suppresses EZH2 activity and inhibits tumor migration and invasion via degradation of EZH2 in pancreatic cancer cells." (PMID 30150556, 2018). "On the other hand, MEK/ERK inhibition decreases EZH2 expression in colon and pancreatic cancer lines with both KRASG12C and KRASG12V." (PMID 29851957, 2018). "In our previous studies, we demonstrated that lncRNA IRAIN suppressed apoptosis and promoted cellular proliferation by binding to LSD1 and EZH2 in pancreatic cancer." (PMID 30367681, 2018). "Recently, Jin and colleagues demonstrated that FBXW7 suppresses enhancer of zeste homolog 2 (EZH2) activity and inhibits tumor migration and invasion via degradation of EZH2 in pancreatic cancer cells." (PMID 29348852, 2017). "Genetic depletion of EZH2 sensitizes pancreatic cancer cells to doxorubicin and gemcitabine, leading to induction of apoptosis." (PMID 28561778, 2017). "EZH2 is reported to be highly expressed in pancreatic cancer cells, known to silence E-Cadherin and it has also been implicated in MMPs activation." (PMID 28881737, 2017). "In this study, we investigated EZH2 expression in pancreatic cancer, assessed its biological functions, and performed an initial analysis of its molecular mechanisms of action." (PMID 26848980, 2016). "We next correlated EZH2 expression with clinico-pathological features in pancreatic cancer patients." (PMID 26848980, 2016). "Taken together, our results indicated that EZH2 promotes pancreatic cancer migration and invasion, possibly through the repression of E-cadherin expression, leading to a poor prognosis in pancreatic cancer patients." (PMID 26848980, 2016). "Subsequent studies showed that EZH2 is upregulated in various solid malignancies including renal cell carcinoma, lung, hepatocellular, gastric, and pancreatic cancer." (PMID 27793053, 2016). "We also examined transcription factor expression and found that ZEB1 and Snail expression were decreased after EZH2 silencing in pancreatic cancer cell lines." (PMID 26848980, 2016). "Of 84 tumor tissue samples, 42 (50%) pancreatic cancers had high EZH2 expression, whereas only 7 (8.3%) had high expression in adjacent non-tumor tissues." (PMID 26848980, 2016). "EZH2 knockdown in pancreatic cancer cell lines inhibited cell migration and invasion, but did not alter cell proliferation." (PMID 26848980, 2016). "To investigate the role of EZH2 in pancreatic cancer cell proliferation, we decreased EZH2 expression in AsPC-1 and CFPAC-1 cell lines using EZH2-siRNA." (PMID 26848980, 2016). "We found that EZH2 expression is up-regulated in pancreatic cancer tissues and positively correlated with lymph node metastasis and advanced clinical stage in pancreatic cancer patients." (PMID 26848980, 2016). "Silencing of EZH2 also increased E-cadherin expression in vitro, and E-cadherin expression was inversely correlated with EZH2 expression in pancreatic cancer tissue samples." (PMID 26848980, 2016). "Its role in pancreatic cancer remains to be clarified; therefore, we investigated the effects of aberrantly expressed EZH2 on pancreatic cancer." (PMID 26848980, 2016). "We used a transwell migration assay to examine the effect of EZH2 on pancreatic cancer cell migration and invasion." (PMID 26848980, 2016).